CD63 (CD63 molecule)
Diseases named in the same sentence as CD63 in open-access papers (continued):
Sharing a sentence is not in itself a finding about the gene and the disease.
tumor (continued). "Further potential applications include minimal residual disease monitoring, as the natural abundance of EVs in the aqueous humor allows us to monitor changes, including the clearance of tumor-derived EVs and the restoration of CD63 dominance." (PMID 39519212, 2024). "While it is not clear which class of EVs, or both, would carry tumor aEGFR, we will validate CD63+ EVs as a tumor aEGFR carrier in this study." (PMID 38830977, 2024). "TIMP1, together with its binding protein CD63, has emerged as a predictive biomarker with regard to tumor therapeutic response and spreading." (PMID 36906579, 2023). "The main marker proteins of tumor exosomes are CD63 and CD81, which are widely found in the peripheral blood and body fluid." (PMID 38045487, 2023). "On the other hand, some TSPAN family members, such as CD82, TSPAN6, TSPAN9 and CD63, exhibit tumor suppressor properties." (PMID 36941633, 2023). "More recently, it has been shown that TIMP-1 secreted by carcinoma-associated fibroblasts stimulates breast cancer cell-dependent secretion of TIMP-1, which in turn cooperates with CD63 and integrin β1 to promote tumor cell growth and migration." (PMID 37443843, 2023). "In order to test if tEVsCSC preferentially interact with specific immune cell subsets, we challenged mice with mEER tumor cells carrying the ALDH1A1:CD63-eGFP or the SRE:CD63-eGFP expression cassette." (PMID 36735677, 2023). "These analyses showed that mEER SRE:CD63-eGFP cells carried on average 30 LV copies per cell (CpC), and that 5 CpC were detected in mEER ALDH1A1:CD63-eGFP cells, indicating full transduction of the tumor cell populations." (PMID 36735677, 2023). "CD63/81+ sEVs enrich AH from RB eyes before treatment and those with more significant tumor burden, suggesting they are tumor-derived." (PMID 37410475, 2023). "As expected, the constitutive reporter (PGK:CD63-eGFP+) showed green fluorescence in virtually all tumor cells." (PMID 36735677, 2023). "For example, TNBC (serum or cell line) produced the smallest number of EVs, whilst the highest concentration of EVs was detected in ER+HER2+ cancers, reflecting the higher level of CD63+ vesicles found within its local tumour microenvironment." (PMID 37441083, 2023). "Remarkably, in another module, the TIMP1 ligand secreted by CAFs bound to the receptor CD63 on the surfaces of tumor cells and TAMs, whereas the SPP1 ligand secreted by APOC1+SPP1+ TAM cells bound to the ITGB1 receptor on CAFs." (PMID 37333982, 2023). "At the same time, in a cohort of patients with CRC, the exosomal marker CD63 expression was lower in tumor tissue compared to adjacent normal mucosa." (PMID 37241967, 2023). "To this end, we performed immunofluorescence staining for CD45 and F4/80 on tumor sections from mice carrying either PGK:CD63-eGFP or ALDH1A1:CD63-eGFP expressing tumors." (PMID 36735677, 2023). "Given that the EV marker expression of CD63 in tumour tissues using immunohistochemistry has been shown to be feasible, we examined the expression patterns of CD63 staining in a tissue microarray (TMA) of early BC patients (n = 218)." (PMID 37441083, 2023). "After tumor removal (postoperation), CD63 levels were increased, indicating increased EV levels in the peripheral blood (P = 0.0092)." (PMID 36931723, 2023). "Of note, mSca is ubiquitously expressed by all tumor cells under the control of a constitutive bi-directional promoter, along with CD63-eGFP, whereas SrtA is specifically expressed by CSC under the regulation of the ALDH1A1 promoter." (PMID 36735677, 2023). "Because the CD63/81+ sEV subpopulation was increased in RB eyes prior to treatment, we believe these sEVs are tumor-derived." (PMID 37410475, 2023). "Upon staining vesicles for typical tumor biomarkers, the presence of surface receptors CD63, CD81, and TSG-101 was demonstrated." (PMID 37886937, 2023). "Results showed that CD63-GFP-expressing EV was most significantly ingested in the primary tumor and the liver from 12-h post-injection." (PMID 37941082, 2023).
tumor (continued). "CD9 (Tspan4) and CD81 (Tspan28), depending on tumor type, can promote or suppress disease progression, while some other Tspan proteins, such as CD82 (Tspan27) and CD63 (Tspan30), have solely been established as tumor suppressors." (PMID 36143328, 2022). "CD63 expression is the second highest overall; this tetraspanin has been described as carrying both tumor suppressor as well as protumorigenic properties and is a predictor of poor prognosis in several cancers." (PMID 36555738, 2022). "To confirm this result, we co‐stained the tumour sections with fluorescent anti‐human CD63 and anti‐human ITGAV antibodies and examined them using confocal microscopy." (PMID 35923105, 2022). "Other features, such as CD63, were identified, which overexpression negatively regulated tumor invasiveness, including HCC." (PMID 36457491, 2022). "Differential expression analysis of the hyperexpanded clones compared to all other clones revealed an elevated expression of tumor promoting factors/oncogenes (HSPA5, PDIA4, MANF, PPIB) and a gene associated with malignant B cell clones (CD63)." (PMID 36153593, 2022). "The exosome samples were first detected by Western blotting for exosomal markers, and the results showed all 4 types of tumor cell-derived exosomes expressed CD63 and CD81." (PMID 35200349, 2022). "IL-33 induces basophils to increase expression of a degranulation marker (CD63) and granzyme B, enhancing tumor-killing ability in vitro." (PMID 36291105, 2022). "The serum CD63+-EV levels reflected the tumor burden since they decreased after surgical resection and fluctuated together with CD19-9 levels." (PMID 35350978, 2022). "The expression of CD63 (typical small EVs/exosome marker) in tumor tissues was analyzed by IHC to identify the effect of GW4869 on EVs biogenesis in the tumor tissue." (PMID 36176762, 2022). "Conversely, TM4SF5 affects the internalization of CD63 (a tumor suppressor) from the PM to lysosomes." (PMID 35123128, 2022). "In the present study, we demonstrated for the first time that tetraspanin CD63 is a potential tumour suppressor in HCC." (PMID 33277798, 2021). "In this study, tumour-derived EVs were first captured by CD63-aptamer-modified microbeads followed by addition of two aptamers targeting the membrane proteins EpCAM and HER2 on EVs." (PMID 34855021, 2021). "The tumor post-NCCR resected rectum mean CD63 score was 155 in patients with low-intermediate NAR scores compared to 180 in patients with high NAR scores (P = 0.3793)." (PMID 34316329, 2021). "A similar correlation between high expression of CD63 and larger tumor size, as well as increased vascular and stromal invasion, and higher mortality was observed in our analysis." (PMID 34065085, 2021). "The mean tumor CD63 score in pre-NCCR rectal biopsy vs. post-NCCR resected rectum was 106 vs. 165 (P = 0.0022)." (PMID 34316329, 2021). "We next wanted to investigate the impact of CD81+CD63+EV secretion on the functional properties of the 67NR tumor cells." (PMID 34503207, 2021). "CD9, CD63, and CD81, in conjunction with other tetraspanins, promote (in association with exosomes) cancer cell motility, invasion, metastasis, tumor initiation, promotion, progression, and angiogenesis." (PMID 33669943, 2021). "When overexpressing miR-185-5p or interfering with RAB35, we observed suppressed TSG101 protein and CD63 protein expression in tumor cells and their derived exosomes." (PMID 34500436, 2021). "The mean tumor CD63 and CD9 scores respectively in pre-NCCR biopsy was 99 and 130 in patients with low-intermediate NAR score compared to 117 and 144 in patients with high NAR score (P = 0.4934) (P = 0.5519)." (PMID 34316329, 2021). "Exposure to NCCR resulted in an increase in the tumor exosomal markers (CD63 and CD9) expression in the post-NCCR resected rectum compared to pre-NCCR rectal biopsies." (PMID 34316329, 2021).
tumor (continued). "Flow cytometry (FCM) analysis showed that engineered exosomes marked by CD63 were taken into tumor cells, including 143B, Hela, and A549 cells (P < 0.05)." (PMID 34671604, 2021). "To further verify that the isolated pellets were exosomes, we analyzed levels of the exosome-specific markers (CD9 and CD63) in tumor cells and pellets isolated from their respective media." (PMID 33618729, 2021). "All these studies corroborate the idea that the TIMP-1/CD63/β1-integrin complex modifies the behavior of different types of tumor cells, giving them the ability to migrate, proliferate, and survive." (PMID 34502227, 2021). "Combined in vitro and animal studies with these cell lines suggested that CD81+CD63+EV secretion can impede tumor formation." (PMID 34503207, 2021). "Recently, EpCAM on tumor-derived EV membrane was also employed as a promising tumor surface marker, while the tetraspanin family of proteins, such as CD63, CD9, and CD81, was mainly used as EV universal markers." (PMID 34900726, 2021). "By isolating exosomes from tumor tissues, we noticed that the CD63 and the PD-L1 in the HGF NPs group was barely visible, suggesting the remarkable inhibition of GW4869 to the tumoral exosome and exosomal PD-L1." (PMID 34593794, 2021). "Our clinical investigation showed that CD63 expression was frequently down‐regulated in HCC tissues, and reduced CD63 expression was associated with larger tumour size, distant site metastasis and higher TNM stages." (PMID 33277798, 2021). "Since DC EVs can present tumor peptides to cytotoxic T cells and regulate immune responses via the presence of major histocompatibility class I and II proteins and tetraspanin CD63 on their surface, they also have great potential in tumor treatment." (PMID 34829963, 2021). "The results showed that CD63 was frequently down‐regulated in tumour tissues compared with adjacent normal tissues at protein level." (PMID 33277798, 2021). "The protein expression of CD63 in a tissue microarray (TMA) consisting of 75 HCC tumour tissues and paired adjacent normal tissues was analysed by immunohistochemistry." (PMID 33277798, 2021). "The mean tumor CD63 and CD9 scores respectively in post-NCCR resected rectum was 155 and 205 in patients with low-intermediate NAR score compared to 180 and 230 in patients with high NAR score (P = 0.3793) (P = 0.2837)." (PMID 34316329, 2021). "The tumor lesion in the bone exhibited abundant expression of exosomal marker CD63, implying exosome activity in the microenvironment." (PMID 34465793, 2021). "This proximity ligation approach was additionally verified for the sensitive detection of tumour-derived exosomal PD-L1/CD63, and exosomal CD63/EpCAM/MUC1 using multiple fluorophore coded aptamers." (PMID 34855021, 2021). "As expected, CD63 overexpression significantly inhibited tumour growth of Huh7 cells, while knockdown of CD63 promoted tumorigenicity of MHCC‐LM3 cells." (PMID 33277798, 2021). "Consistently, CD63 mRNA expression in tumour tissues was remarkably lower than in adjacent normal tissues, and it exhibited a <0.5‐fold decrease in 21/35 (60%) paired tissues." (PMID 33277798, 2021). "CD81+ and CD63+ EVs derived from both tumor cells and fibroblasts were found within both models, suggesting EV release and potential EV internalization by both cell types." (PMID 33968758, 2021). "The tumor pre-NCCR rectal biopsy mean CD63 score was 99 in patients with low-intermediate NAR scores compared to 117 in patients with high NAR scores (P = 0.4934)." (PMID 34316329, 2021). "Whole-body imaging revealed the appearance of the reporter signal in PC3/CD63-Antares2 tumor-bearing mice accompanied with an increase in bioluminescence intensity in the blood." (PMID 33024173, 2020). "Under experimental conditions in which control and CD63-Antares2-expressing cells showed the same tumor growth, the bioluminescence intensity in the blood gradually increased with increasing PC3/CD63-Antares2 tumor size." (PMID 33024173, 2020).
tumor (continued). "Proteins such as CD9, CD63, and CD81 are located on the exosome surface, and tumor-associated markers (HER2, EpCAM) are also present on tumor-associated exosomes." (PMID 32582658, 2020). "A seminal study of paired tumor tissues and CD63+/TSG101+ EVs from the serum of patients with pancreatic cancer reported that EV DNA covered the entire genome, and carried mutations that were identical to the parental tumors." (PMID 33158181, 2020). "Results from Western blotting analysis showed presence of CD63, an exosome marker, in tumor cell-derived exosomes." (PMID 32555395, 2020). "Specifically, patients with high levels of circRNA_0000199 in CD63+/TSG101+ EVs EPs had high tumor recurrence and mortality rates underscoring the prognostic potential." (PMID 33158181, 2020). "CD63 was detectable in all exosomal fractions of tumor samples, and the signal intensity was reduced in fraction 3 (F3), whereas it was detected only in F1 and F2 from normal tissue samples." (PMID 33276608, 2020). "In this context, an anti‐CD63 neutralizing monoclonal antibody was administered with tamoxifen in tumor mouse models." (PMID 33173749, 2020). "As a result, CD63 represents a promising target for not only cancer assessment, but also delivering drugs specifically to CD63-positive tumor cells for precision anti-cancer therapy." (PMID 33261145, 2020). "Western blot analysis demonstrated that all seven types of tumor cell exosomal preparations were enriched in the exosome marker CD63." (PMID 33833900, 2019). "The results showed that the plasmatic levels of CD63+ exosome levels decreased after tumour and lymph node resection surgery, although this decrease does not become significant due to the sample size available." (PMID 30917536, 2019). "IHC staining showed that after the treatment of LMP1‐positive exosomes, the expression of LMP1 was obvious in the tumor tissues, and the expression of CD63 which represents the EVs secretion in tumor tissues and stroma was increased as well." (PMID 31436393, 2019). "CD63 was detected in both fusiform and stellate shaped tumor cells as well as in multinucleated giant cells." (PMID 29523123, 2018). "On the other hand, CD63 positivity in stromal cells was significantly correlated with age (≥65), tumor depth (T3-4), lymphatic invasion, and tumor size (≥ 5 cm)." (PMID 30222750, 2018). "Cases with CD63-positive stromal cells were significantly correlated with age (≥65), tumor depth (T3-4), lymphatic invasion, and tumor size (≥ 5 cm)." (PMID 30222750, 2018). "The expression levels of both TEGTBI-1 and CD63 were down-regulated in tumor tissues of patients treated with TAM." (PMID 29416786, 2018). "Cases with CD63-positive cancer cells were significantly correlated with scirrhous-type gastric cancer, tumor depth, lymph node metastasis, lymphatic invasion, and tumor size." (PMID 30222750, 2018). "TIMP-1 is increasingly recognized as a molecule with a variety of pro-tumorigenic functions, e.g. TIMP-1 can bind to the tetraspanin CD63 and promote liver metastases via both, host-mediated mechanisms as well as direct effects on tumor cell aggressiveness." (PMID 29394913, 2018). "We examined the presence of TNBC cell–derived exosomes using antibodies for the detection of human CD63 in axillary LNs of tumor-bearing mice." (PMID 29484119, 2018). "CD63 positivity in stromal cells was significantly correlated with age (≥65), tumor depth (T3-4), lymphatic invasion, and tumor size (≥ 5 cm)." (PMID 30222750, 2018). "In some of the tumors, peripheral tumor areas were present, and these zones contained few diffusely invading and weakly CD63+ putative tumor cells as well as CD63+ pyramidal shaped neurons." (PMID 29523123, 2018). "TIMP-1/CD63 co-expression was detected in tumor biopsies as well as in the organotypic and U87MG cell line-derived spheroids." (PMID 29523123, 2018).
tumor (continued). "In some of the blood vessels, CD63 was faintly expressed and mainly detected close to the lumen of the tumor blood vessels corresponding to the supposed localization of the apical endothelial membrane." (PMID 29523123, 2018). "CD63 tumor cell intensity also increased significantly with tumor grade (p < 0.01 and p < 0.001, respectively)." (PMID 29523123, 2018). "The use of InP/ZnS–Anti-CD63 conjugates for the purposes of signal amplification has been observed for tumor markers using SPR, as well with the further use of a gold nanoparticle for dual signal amplification, which led to a 50-fold increase." (PMID 30279349, 2018). "This analysis showed that the patients in the NAC group had significantly lower CD63 protein levels (P = 0.010) compared to the corresponding tumor samples before the CDDP treatment." (PMID 30367559, 2018). "This method is highly specific, allowing the isolation of only small EVs by using general small EV surface markers (e.g., CD81, CD9, and CD63) and even only small EV subpopulations, for example, tumor small EVs by using a tumor-specific marker." (PMID 29951374, 2018). "We used the exosomes marker CD63 antibody and red blood cell marker CD235a antibody to validate the exosomes in tumor tissue by immunohistochemistry (IHC)." (PMID 28650446, 2017). "The intensity of the band of CD63 was higher in the exosomes from tumour tissues and plasma of CRC patients than that in the normal tissue lysates and plasma exosomes from healthy individuals." (PMID 28233416, 2017). "Exosomes were collected from tumor cell culture media by ultracentrifugation Their identity was confirmed by electron microscopy and the presence of CD63, HSP70 and TSG101, known exosome specific markers." (PMID 26337469, 2015). "We detected tetraspanin proteins (CD9, CD63, CD81), Alix and tumor susceptibility gene-101 (TSG101) of exosomal markers from rotenone treated CSCs." (PMID 25682864, 2015). "TM4SF5 interacted with CD151, and caused the internalization of CD63 from the cell surface into late lysosomal membranes, presumably leading to terminating the tumor-suppressive functions of CD63." (PMID 25033048, 2014). "Similar to TM4SF1, TM4SF5 expression resulted in the internalization of CD63 from the cell surface to the lysosomes, thus decreasing CD63 level on the membrane surface and reducing its tumor suppressive actions." (PMID 25033048, 2014). "RPN2 silencing resulted in reduced CD63 glycosylation and deregulated localization in tumor cells, which regulates drug resistance and tumor cell invasion." (PMID 25181275, 2014). "Data obtained from these co-immunoprecipitation assays using cell lines representing different stages of melanocyte malignant transformation show differential interaction among CD63, Timp1 and β1-integrin along tumor progression." (PMID 23522389, 2013). "Tumor cells strongly expressed CD63, vimentin, and NKI-C3, while desmin, smooth muscle actin (SMA), S100, CK7, CK20, CK5/6, epithelial membrane antigen (EMA), P63, CD1a, and MART-1 were all negative." (PMID 23691398, 2013). "The tetraspanin superfamily proteins (TM4SF) mainly CD9, CD63, CD82, CD151 and CD81 have been implicated in cell migration, proliferation and tumor cell metastasis." (PMID 23128478, 2013). "Human CD63 was first reported as the ME491 antigen, a tumour marker and is now more commonly known as a marker of lysosomes and multivesicular bodies." (PMID 21625559, 2011). "Exosomes were purified from plasma of tumor patients (n = 90) and healthy donors (n = 58) and quantified by Exotest based on the expression of CD63 and Cav1." (PMID 19381331, 2009). "So far, our results identified glycosylation macroheterogeneity as a critical determinant of the tumor-promoting cytokine-like activity of TIMP-1 via CD63, which would be one explanation for the correlation of elevated expression of double-glycosylated TIMP-1 in PC." (PMID 40345589, 2025).